CXCR2 (C-X-C motif chemokine receptor 2)
Diseases named in the same sentence as CXCR2 in open-access papers (continued):
Sharing a sentence is not in itself a finding about the gene and the disease.
infection (continued). "This prediction was consistent with our previous observations where Cxcr2 knockout mice that cannot recruit neutrophils to the site of infection, survived challenge without any detectible changes in pathogen load." (PMID 22438999, 2012). "Infection of CXCR2−/− mice with JHMV did not recapitulate our observations with infected wildtype mice treated with CXCR2 antiserum." (PMID 19893623, 2009). "However, in contrast to this trend, we identified elevated levels of the chemokine receptor gene, CXCR2, in the KO neonatal mice during infection that did not change significantly in WT pups." (PMID 40977737, 2025). "In contrast, there was no change in CXCR2 expression during infection in neutrophils from KO pups." (PMID 40977737, 2025). "IL-8 binds with high affinity to the G protein-coupled receptors CXCR1 and CXCR2, and the Duffy antigen receptor for cytokines, CXCR1, formerly known as the IL-8 type A receptor, which responds to high concentrations of IL-8, is most often found at sites of infection." (PMID 39062898, 2024). "Histological findings of immune cell infiltration in tracheal tissues after infection with swH1N1 was in line with induction of cytokines and chemotactic factors (AMCF-II, CXCL8/IL8, CXCL2, CXCL10, and CCL20) as well as receptors (CCR1 and CXCR2) in lower trachea after this infection." (PMID 39247193, 2024). "Moreover, CCL2, CCL21, CXCL2, CXCR2, and CXCR3 mRNAs were significantly induced at 6–12 h after V. harveyi infection, implying that P. leopardus immune cells can be activated and recruited to the sites of infection at early time points post-infection." (PMID 39450165, 2024). "Flow cytometric analysis confirmed that the depletion of neutrophils was successful and that neutrophils remained absent following infection, this was confirmed by a reduction in the CD11b+/CXCR2+ population of cells from 18% in the blood of isotype control animals to 0.45% in depleted animals." (PMID 35529317, 2022). "Moreover, significantly increased CXCR2 gene expression in the HF + G group suggests neutrophils migrated to the site of infection; a phenomenon not observed in LF + G mice." (PMID 34552170, 2021). "By analyzing at the molecular level the mechanisms of pituitary dysfunction, we showed that in the absence of Cxcr2, bystander infections affect leukocyte migration, adhesion, and function, as well as ion transport, synaptic function behavior, and reproduction pathways." (PMID 32041848, 2020). "Further guidance to sites of infection is provided by a family of CXCL8 chemokines originating from concentrated sites of PAMPs and DAMPs, including CXCL1, CXCL2, CXCL3, CXCL5, CXCL6, CXCL7, and CXCL8 (IL-8), which are sensed by CXCR1 and CXCR2 on neutrophils and monocytes." (PMID 30791481, 2019). "In contrast, although the total observed and estimated taxa (Chao1) were not different across the groups after RRV infection, exposure to SMZ/TMP or the loss of Cxcr2 induced significantly lower Dominance and higher Shannon H index, indicating more diverse bacteria." (PMID 28763485, 2017). "Finally, i.p. infection of CXCR2−/− mice with JHMV did not affect the generation of virus-specific CD4+ or CD8+ T cells compared to infected CXCR2+/+ mice." (PMID 19893623, 2009). "While a lack of CXCR2 appears to worsen infection, it is unknown if augmenting CXCR2, and therefore potentially improving neutrophil migration, might prove an effective means of promoting infection clearance." (PMID 38567642, 2024). "This may be because the bacteria can induce cellular senescence even in the absence of an active infection by upregulation of cytokines, such as tumor necrosis factor-alpha and interleukin-1 beta, which may induce through NFKB1 to activate CXCR2 signaling." (PMID 40051725, 2025). "Studies in IL-8 Receptor 2 knockout (IL-8R2−/−, also known as CXCR2−/−) mice on a BALB/c background suggest that PMN’s may not play a protective role in experimental mouse infection." (PMID 38535182, 2024).
infection (continued). "Furthermore, the higher expression of chemokine (CXC motif) receptor 2 (Cxcr2), Fc gamma receptor III [Fcgr3 (Cd16)], and ferritin heavy chain (Fth1) in clusters 0, 1, 2, 4, and 5 indicated the presence of migrating and maturing neutrophils, regardless of infection status." (PMID 38767331, 2024).
bacterial infection (17 papers, 2012 to 2024). "Lcn2, also called neutrophil gelatinase-associated lipocalin (NGAL), induces CXCR2 and has been shown in mice to be important for promoting neutrophil migration and protective against bacterial infection." (PMID 38567642, 2024). "However, CXCR2 is a major trafficking receptor for neutrophils and thus blocking CXCR2 may increase susceptibility to bacterial infection." (PMID 34885241, 2021). "The researchers found that CCR2+ monocytes produced high levels of CXCL1, which directly recruited CXCR2-expressing neutrophils to the lungs, contributing to the host defense against bacterial infection." (PMID 38596679, 2024). "The chemokine receptor CXCR2 is largely responsible for driving PMN migration during bacterial infection and inflammation." (PMID 37533081, 2023). "In contrast, G-CSF can also impede the CXCR2-induced neutrophil mobilisation by negatively regulating CXCR2-mediated intracellular signalling which under specific bacterial infections, functions as a negative regulator of neutrophil mobilisation." (PMID 34966386, 2021). "In line, expression of the main receptor CXCR2, which is responsible for granulocyte recruitment during bacterial infections, was reduced on granulocytes by Tacrolimus during UTI." (PMID 30643171, 2019). "Whilst the bacterial infection increased CXCR1 expression but decreased CXCR2 expression, PKD enhanced CXCR2 expression at all stages of clinical disease." (PMID 24613851, 2014). "This is a remarkable result considering that absence of CXCR2 is known to negatively impact the overall health status of the mice, which in fact appear runt and are more susceptible to several bacterial infections." (PMID 25166912, 2014). "CXCR1 has been shown to be downregulated in human neutrophils during bacterial infection, whereas in septic patients with organ dysfunction and septic shock, CXCR1 expression was preserved and CXCR2 expression was significantly downregulated." (PMID 28878779, 2017).
inflammation (16 papers, 2013 to 2025). Aberrant reaction of the microcirculation characterized by movement of fluid and leukocytes from the blood into extravascular tissues. "Monocytes' contribution to cardiac inflammation and fibrosis is further exemplified by the altered expression of CXCR2 and TGF-β1, critical factors in monocyte migration and fibrosis." (PMID 38948064, 2024). "In this study, we found most cardiac infiltrated CXCR2+ macrophages are M1 subset, indicating that UA-induced cardiac inflammation is largely via activation of M1 subset." (PMID 34385934, 2021). "It has been shown that CXCR2 signaling is essential for rhinovirus-induced neutrophilic airway inflammation and development of airway hyperresponsiveness in murine model in vivo." (PMID 30804927, 2019). "The results predict that neutrophil depletion or the pharmacological targeting of CXCR2 should protect wild‐type mice from acinar cell damage and pancreatic inflammation." (PMID 25950520, 2015). "In an ozone-induced model of airway inflammation the CXCR2 antagonist SB-656933 inhibited CXCL1-induced CD11b expression on peripheral blood neutrophils and reduced neutrophilic inflammation in sputum." (PMID 23834268, 2013). "Moreover, acute pancreatic inflammation was reversible by inhibition of CXCR2." (PMID 25950520, 2015). "In line with our findings, it has previously been shown that blockade of CXCR2, the principal neutrophil cognate receptor for CXCL1, suppresses neutrophil infiltration and exerts protection against lung inflammation in aged mice." (PMID 38918502, 2024). "Taken together, the current transcriptomic findings revealed anti-UC pharmacological targets, including the newly discovered biotargets CCL11, CCL21, CXCL3, and CXCR2, of mesalazine against DSS-induced intestinal inflammation." (PMID 34456974, 2021).
cardiovascular diseases (9 papers, 2017 to 2024). "Previous studies show that CXCR2 activation can be cardioprotective or pathogenic, depending on the cardiovascular disease." (PMID 36936778, 2023). "Blocking the CXCR2 pathway primarily inhibits the development of cardiac inflammation and may help to improve the prognosis of inflammation-related cardiovascular diseases." (PMID 35668739, 2021).
peripheral neuropathy (5 papers, 2017 to 2023). A disorder affecting the peripheral nervous system. "Furthermore, KC was found to have a central role in the pathophysiological process of peripheral neuropathy also evident by a reduction in neuropathic pain upon pharmacological blockade of KC receptor- CXCR2 by the selective antagonist." (PMID 35273508, 2022).
infectious disease (4 papers, 2010 to 2025). A disorder directly resulting from the presence and activity of a microbial, viral, or parasitic agent in humans. "We checked the expression of CXCR2, which is the main chemokine receptor on neutrophils for CXCL1 and CXCL2, because expression of CXCR2 is critically important for neutrophil associated protection against various infectious diseases." (PMID 28817707, 2017). "In infectious diseases, CXCR2 and CXCR1 are also recognized as key regulators of NET formation." (PMID 40625358, 2025).
metabolic disorders (4 papers, 2023 to 2025). "Further in vivo studies discovered using mouse models that inducting CXCR2 was found to worsen steatohepatitis and antagonizing CXCR1 and CXCR2 protected mice from metabolic disease by a modulation of the inflammatory process." (PMID 37887430, 2023).
neurodegenerative disease (4 papers, 2012 to 2025). A disorder of the central nervous system characterized by gradual and progressive loss of neural tissue and neurologic function. "CXCR2 has been implicated in remyelination processes in preclinical models of demyelination, suggesting its potential as a therapeutic target in neurodegenerative diseases." (PMID 41259376, 2025). "CXCR2 upregulation has been linked to a myriad of inflammatory disorders (such as asthma, chronic obstructive pulmonary disease, cystic fibrosis), autoimmune diseases (e.g., rheumatoid arthritis and psoriasis), and even neurodegenerative diseases (such as multiple sclerosis and Alzheimer’s disease)." (PMID 36903345, 2023).
respiratory diseases (4 papers, 2019 to 2024). "Several reports have suggested that the CXCR2 variants might influence the susceptibility to chronic inflammatory conditions, especially rheumatoid and respiratory diseases." (PMID 30863202, 2019).
retinopathy (3 papers, 2022 to 2025). "CXCR2 was the dominant ELR+ CXC chemokine receptor expressed in retinal ECs, and CXCR2 deficiency abolished the therapeutic effect of PTGFR inhibition on retinopathy in OIR mice." (PMID 36511116, 2023). "Above all, these results suggest that Ang II infusion could upregulate the expression of CXC chemokines, leading to the increased infiltration of circulating CXCR2+ myeloid cells into the retina, which may be associated with retinopathy." (PMID 35981418, 2022). "Our study focused on the effect of CXCR2 expressed on monocytes/macrophages on Ang II-induced retinopathy." (PMID 35981418, 2022). "To explore the function of the CXCL1-CXCR2 axis in Ang II-induced retinopathy, we used CXCR2 knockout (KO) mice and C57BL/6J wild-type (WT) mice as experimental subjects." (PMID 35981418, 2022). "Whether it is through VEGF-dependent or independent mechanisms, it is likely that CXCR2 activation by ligands such as IL-8 plays an important role in human angiogenic retinopathies." (PMID 41176546, 2025). "However, CXCR2 deletion suppressed proliferative retinopathy in OIR mice." (PMID 36511116, 2023). "Thus, CXCR2 ablation can ameliorate Ang II-induced retinopathy." (PMID 35981418, 2022). "Importantly, the Ang II-induced response was remarkably reversed in the retinas of CXCR2 KO mice, suggesting that CXCR2 KO not only attenuates the proinflammatory response but also alleviates vascular leakage and BRB breakdown, which protects against Ang II-induced retinopathy in mice." (PMID 35981418, 2022). "Likewise, in vivo, in the oxygen-induced retinopathy (OIR) model, either genetic (Cxcr2-/-) or pharmacologic (SB225002) CXCR2 inhibition reduced pre-retinal neovascularization without altering avascularity or VEGF expression." (PMID 41176546, 2025).
cardiac disease (1 paper, 2021). "In summary, exosomal ALPL and CXCR2 have the predictive potential to provide greater accuracy and identification of cardiac disease." (PMID 34490374, 2021).
central nervous system disorder (1 paper, 2024). A disease involving the central nervous system. "Accumulating evidence indicates CXCR2 antagonist, SB332235 possesses anti-inflammatory properties in central nervous system disorders." (PMID 37702890, 2024).
renal diseases (1 paper, 2013). "It would indeed be a promising research direction to investigate whether CXCR2 could act as a potential therapeutic target for IgAN, and other renal diseases that have a phenotype that involves podocyte dysfunction." (PMID 24023680, 2013).
CXCR2 also shares sentences with these, for which no sentence is quoted: intrahepatic cholangiocarcinoma (5 papers); metastatic colorectal cancer (5); adenocarcinoma (4); chorioamnionitis (4); chronic periodontitis (4); kidney (4); acute kidney injury (3); atopic dermatitis (3); allergic asthma (2); Bovine mastitis (2); Brain Tumor (2); Crohn disease (2); digestive system neoplasm (2); Kaposi's sarcoma (2); knee osteoarthritis (2); Lewis lung carcinoma (2); myocardial inflammation (2); nematode infection (2); osteomyelitis (2); peripheral nerve injury (2); skin cutaneous melanoma (2); squamous cell carcinoma (2); thymoma (2); acute promyelocytic leukemia (1); amyotrophic lateral sclerosis (1); anaphylaxis (1); astrocytic tumor (1); Atrophy (1); B-cell lymphoma (1); benign prostate hyperplasia (1).
A further 84 diseases each share a sentence with CXCR2 in 1 paper.